INS (insulin)
Diseases named in the same sentence as INS in open-access papers (continued):
Sharing a sentence is not in itself a finding about the gene and the disease.
Insulin resistance (continued). "Some protocols included the use of ethinylestradiol and cyproterone acetate as pretreatment or insulin sensitizers like metformin in patients with insulin resistance." (PMID 41496930, 2026). "After treatment, significant decreases were observed in body mass index (BMI), Global Acne Grading System scores, androstenedione, fasting insulin, the homeostasis model assessment of insulin resistance index, and total antioxidant capacity (P < 0.05)." (PMID 41607469, 2026). "M1 macrophages contribute to insulin resistance by impairing insulin signaling pathways and sustaining tissue inflammation." (PMID 41556049, 2026). "A systematic review and meta-analysis aimed to assess the effect of SCFA interventions on fasting glucose, fasting insulin, and homeostatic model assessment of insulin resistance (HOMA-IR) has been recently published." (PMID 41596635, 2026). "We showed that oxidative stress and subsequent activation of the JNK pathway were involved in both pancreatic β-cell dysfunction and insulin resistance in various insulin target tissues such as the liver, adipose tissues and skeletal muscle." (PMID 41585322, 2026). "Serum insulin level, an important compensatory marker of insulin resistance, plays a key role in the development and progression of NAFLD." (PMID 41560026, 2026). "Specifically, oxidative stress increases insulin resistance through mechanisms such as inhibition of insulin signaling and the promotion of inflammatory processes." (PMID 41521729, 2026). "In males, NC was further positively correlated with key metabolic biomarkers including fasting insulin, Insulin Resistance Index, triglycerides, and creatinine." (PMID 41745576, 2026). "Fasting insulin levels and the homeostasis model assessment of insulin resistance (HOMA-IR) have been examined in relation to MRS-derived neurometabolites, although available data remain limited and region-specific." (PMID 41596611, 2026). "For example, to maintain euglycemia, islet cells respond to mild glucose elevations accompanying insulin resistance with increased insulin secretion and cellular hypertrophy, establishing a higher blood insulin level (hyperinsulinemia)." (PMID 41268722, 2026). "In an animal model of high-fat diet-induced insulin resistance, impaired insulin signaling activates FoxO3a, disrupting AMPA receptor trafficking and weakening synaptic plasticity, leading to cognitive impairments." (PMID 40819304, 2026). "Background/Objectives: Impairment in pulsatile insulin release contributes to insulin resistance and is one of the earliest markers of developing type 2 diabetes." (PMID 42042909, 2026). "Insulin resistance was defined by the lowest quartile of the Matsuda Index (≤2.80); insulin secretion by the Insulin Secretion Index (ISI)." (PMID 41850717, 2026). "These include accentuated insulin resistance and hyperglycemia because pancreatic β-cells also become increasingly senescent with reduced ability to secrete insulin, and SASP factors impair insulin receptor signaling in metabolic cells." (PMID 41189469, 2026). "Glucose tolerance, fasting glucose and insulin levels, homeostasis model assessment of insulin resistance (HOMA-IR), lipid profile, fructosamine, and thiobarbituric acid reactive substances (TBARSs) were evaluated." (PMID 41829928, 2026). "In T2D, insulin resistance and impaired insulin secretion exist, and while protein can stimulate insulin secretion, the efficacy of that insulin in lowering blood glucose can be blunted." (PMID 41602572, 2026). "Specific changes in its phosphorylation result in impaired insulin signaling, which is an established pathological marker of insulin resistance in peripheral tissues." (PMID 41326666, 2026). "Collectively, these findings demonstrate that TXA mitigates TNF-α-induced insulin resistance by improving insulin signaling, suppressing inflammation and oxidative stress, and improving lipid and mitochondrial metabolism." (PMID 41835598, 2026).
Insulin resistance (continued). "Hyperinsulinemia can be an effective compensatory mechanism that preserves insulin action in mild and moderate insulin resistance." (PMID 41543803, 2026). "Multicollinearity among insulin resistance indices (VIF > 20) indicates overlapping variance among insulin, HOMA-IR, and QUICKI, as reported in other metabolic modeling studies." (PMID 41596434, 2026). "As a representative member of the CTRP family, adiponectin enhances insulin sensitivity and improves insulin resistance." (PMID 41524288, 2026). "Increased sympathetic nervous system activity has inhibitory effects on insulin secretion and promotes insulin resistance and the development of the metabolic syndrome." (PMID 41601938, 2026). "Concurrently, insulin resistance (IR), a pathophysiological state characterized by diminished cellular responsiveness to insulin, presents a complex and multifactorial metabolic derangement." (PMID 41878578, 2026). "Future research should focus on region-specific effects of insulin resistance and identify patient subgroups likely to benefit from insulin-based interventions." (PMID 40819304, 2026). "Insulin levels increased markedly after glucose loading in all participants, reflecting generalized insulin resistance, but showed limited ability to discriminate between complication phenotypes." (PMID 41750337, 2026). "In obesity, progressive peripheral insulin resistance leads to impaired insulin transport across the BBB and the development of central insulin resistance." (PMID 41596611, 2026). "Overall, these findings indicate that the stem hydroalcoholic extract effectively counteracts palmitic acid–induced insulin resistance in L6 myotubes by restoring the phosphorylation of key components of the insulin signaling pathway." (PMID 41599356, 2026). "For example, inducible deletion of GRK2 in mice reverses diet-induced obesity and insulin resistance, mitigates hepatic steatosis, and improves insulin sensitivity." (PMID 41602450, 2026). "In the dexamethasone-induced insulin resistance model, LASSBio-1986 restored insulin sensitivity, as evidenced by improved insulin tolerance test responses and partial normalization of glycemic excursions following exogenous insulin administration." (PMID 41596477, 2026). "In vivo, sinapine improved glucose/lipid metabolism and insulin sensitivity, revealing its molecular mechanism for mitigating insulin resistance." (PMID 41497732, 2026). "Cardio-renal metabolic (CRM) syndrome, characterized by insulin resistance and dyslipidemia, disrupts renal insulin signaling, enhances oxidative stress, and activates inflammasome pathways, ultimately promoting renal fibrosis and kidney dysfunction." (PMID 42193257, 2026). "Regarding insulin sensitivity and in line with findings from our study, male individuals show greater prevalence and development of insulin resistance." (PMID 41525266, 2026). "Regular physical activity exerts systemic anti-senescence effects by lowering plasma insulin levels, alleviating insulin resistance, enhancing mitochondrial function, and reducing inflammation across multiple tissues." (PMID 41189469, 2026). "This cluster was characterized by low insulin clearance, high insulin resistance, elevated Hepatic‐IR and Adipo‐IR, being more pronounced in women than in men." (PMID 41133433, 2026). "Over 12 and 24 months, improvements occurred in HbA1c, fasting insulin, Homeostatic Model Assessment for Insulin Resistance (HOMA-IR), and the Matsuda index in SG vs. NS (p ≤ 0.002)." (PMID 41829904, 2026). "PGS differs from LS due to higher insulin secretion, low insulin clearance, and increased hepatic insulin resistance." (PMID 41133433, 2026). "Type 2 diabetes (T2D) is a growing global health concern characterized by peripheral insulin resistance and impaired insulin secretion from pancreatic β-cells." (PMID 42278312, 2026).
Insulin resistance (continued). "Anthropometric parameters, fasting glucose, insulin, lipid profile, and the Homeostasis Model Assessment of Insulin Resistance (HOMA-IR) index were assessed in all participants." (PMID 41897113, 2026). "Insulin resistance in obesity and type 2 diabetes (T2D) is characterized by reduced insulin-stimulated glucose uptake, accumulation of triacylglycerol, mitochondrial dysfunction, and altered protein metabolism in skeletal muscle." (PMID 42017540, 2026). "Reduced fasting obestatin and postprandial concentrations have been reported in patients with T2DM and insulin resistance while a positive correlation between fasting obestatin and insulin sensitivity has been observed in healthy adults." (PMID 41575482, 2026). "In T1DM, weight gain reflects intersecting drivers, including intensive insulin therapy, hypoglycemia-related compensatory intake and activity avoidance, obesity-related insulin resistance, and overlapping genetic/hormonal determinants." (PMID 41721160, 2026). "At baseline, participants exhibited elevated glucose, insulin, homeostatic model assessment for insulin resistance (HOMA-IR), triglycerides, and C-reactive protein (CRP) levels, consistent with insulin resistance and chronic low-grade inflammation." (PMID 41683970, 2026). "Children were divided into two groups as control and insulin resistant according to the homeostatic model assessment of insulin resistance (HOMA-IR)." (PMID 41859967, 2026). "Women with higher ZFP36 expression demonstrated improved insulin sensitivity, marked by lower fasting insulin, reduced insulin resistance (HOMA-IR), and lower insulin after glucose intake." (PMID 41596407, 2026). "A 24-year-old man with no prior autoimmune history presented with diabetic ketoacidosis and severe insulin resistance, requiring up to 215 000 units of insulin daily." (PMID 42211865, 2026). "While tyrosine phosphorylation of IRS-1 promotes insulin action, serine phosphorylation can inhibit insulin signaling, thereby contributing to the development of insulin resistance." (PMID 41599356, 2026). "Given the potential regulatory role of insulin, further research is needed to investigate how insulin resistance and hyperinsulinemia influence inflammasome activity in adipose and other relevant tissues." (PMID 41596350, 2026). "Insulin resistance is central, but fasting-insulin-based indices are impractical for routine screening." (PMID 42137861, 2026). "Proteomics validated higher insulin resistance in STBs alongside elevated insulin secretion, AMPK, mTOR, and MAPK pathway activities." (PMID 41556081, 2026). "Three clusters of nodes emerged, grouping: (a) insulin, glucose and Homeostatic Model Assessment for Insulin Resistance (HOMA-IR index); (b) cholesterol and triacylglycerol; and (c) sociodemographic profile, psychological state, BMI and HTN." (PMID 41515261, 2026). "Individuals in cluster 3 had lowest insulin secretion, cluster 5 had increased intrahepatic lipid content and high insulin resistance." (PMID 41547928, 2026). "The findings consistently showed improvements in fasting glucose levels, insulin sensitivity, and reduction in serum insulin levels and homeostatic model assessment for insulin resistance with increased Quantitative Insulin Sensitivity Check Index scores." (PMID 41370015, 2026). "Skeletal muscle can be affected by insulin resistance (IR), and it is the largest site of insulin-stimulated glucose disposal." (PMID 41753348, 2026). "In streptozotocin-induced diabetic rats, PSE supplementation significantly reduced fasting blood glucose, HbA1c (glycated hemoglobin), and fasting insulin levels and homeostasis model assessment of insulin resistance." (PMID 42294182, 2026). "She became dependent on IV insulin and was diagnosed with severe subcutaneous insulin resistance (SIR)." (PMID 41472947, 2026).
Insulin resistance (continued). "Intriguingly, DM_CKD animals required significantly more insulin to titrate their plasma glucose levels to 300 mg/dL, suggesting that the kidney injury aggravated insulin resistance and DM." (PMID 41419687, 2026). "Fasting insulin, homeostasis model assessment of insulin resistance (HOMA-IR), fasting glucose, and HbA1c were analyzed using survey-weighted linear regression; models were adjusted for demographic, socioeconomic, lifestyle, and adiposity-related factors." (PMID 42194723, 2026). "Western blot analysis showed a strong reduction in ribosomal protein S6 phosphorylation in peripheral tissues (liver, muscle, and adipose) in response to injected insulin, consistent with the presence of peripheral insulin resistance." (PMID 41362820, 2026). "Excess visceral adipose tissue is infiltrated by macrophages, which secrete TNF-α and IL-6, which serve to enhance insulin resistance by modulating the signaling of insulin through peripheral tissues, thus sustaining a pro-diabetogenic vicious circle." (PMID 41590667, 2026). "Bulls exposed to the HG diet had greater (P < 0.01) insulin resistance at the end of the feeding period based on insulin: glucose ratio and revised quantitative insulin sensitivity check index (RQUICKI)." (PMID 41525320, 2026). "Pro-inflammatory cytokines, such as interleukin-6 (IL-6), tumor necrosis factor-alpha (TNF-α), and interleukin-1β (IL-1β), disrupt insulin signaling, impair β-cell function, and exacerbate insulin resistance." (PMID 41578487, 2026). "Concurrently, TIR, insulin levels, C-peptide levels, and insulin resistance (as measured by HOMA-IR) improved, while 2-hour postprandial glucagon (2h-PGlu) decreased." (PMID 42238245, 2026). "A key pathophysiological feature of obesity is insulin resistance, a condition in which insulin‐sensitive tissues (e.g., skeletal muscle, adipose tissue, and liver) exhibit a diminished response to insulin, leading to impaired glucose uptake and hyperglycemia." (PMID 41524084, 2026). "Severe subcutaneous insulin resistance (SIR) is characterized by severe resistance to subcutaneous (SC) insulin but normal intravenous (IV) insulin sensitivity." (PMID 41472947, 2026). "The frequency of elevated markers of insulin resistance (insulin/HOMA-IR) was higher in the EIN/EC groups compared to the leiomyoma group (47% vs. 20%)." (PMID 41595367, 2026). "Marked improvements were observed in insulin sensitivity, with reductions in fasting insulin, glucose, and homeostatic model assessment of insulin resistance (HOMA-IR)." (PMID 41853422, 2026). "The TyG index serves as a surrogate marker of insulin resistance and cannot directly capture detailed insulin dynamics; furthermore, stratification based on the Youden index carries a potential risk of overfitting." (PMID 41601726, 2026). "(2019) studied the metabolite response to an OGTT in individuals with insulin resistance but normal glucose tolerance in comparison to insulin‐sensitive individuals with normal glucose tolerance." (PMID 40551391, 2026). "Dysfunction of the pancreatic insulin-producing B cells and insulin resistance mainly lead to hyperglycemia." (PMID 41594284, 2026). "Fasting blood sugar (FBS), lipid profile, insulin, Homeostatic Model Assessment for Insulin Resistance (HOMA IR), body composition, multiple cytokines, oxidative stress markers and leukocyte telomere length were assessed." (PMID 41898222, 2026). "Beta-C3-KO mice gained more weight, exhibited higher fasting blood glucose and insulin levels, and showed signs of adipose tissue inflammation and insulin resistance." (PMID 41386533, 2026). "High blood insulin levels, resulting from insulin resistance, stimulate the release of insulin-like growth factor-1 (IGF-1), promoting cell growth and division in the body, including in the liver." (PMID 41607999, 2026).
Insulin resistance (continued). "Clinical parameters included body mass index (BMI), waist circumference, blood pressure, lipids (LDL‐c and triglycerides), fasting glucose, HbA1c, fasting insulin (used to calculate HOMA2‐IR for insulin resistance), and C‐reactive protein (CRP)." (PMID 41559012, 2026). "Insulin resistance (IR), characterized by insensitivity of metabolic tissues to insulin stimulation, has emerged as a major impediment to overall metabolic health." (PMID 41667791, 2026). "Glycaemic outcomes, including insulin resistance, prediabetes (impaired fasting glucose) and type 2 diabetes, were assessed using fasting glucose and insulin (ages 7, 15, 18 and 24 years) and HbA1c (age 9 years)." (PMID 41986816, 2026). "This cluster, with the highest BMI, exhibits pronounced insulin resistance, exacerbated by reduced insulin clearance." (PMID 41133433, 2026). "Injection-related pain, fear of needles, local tissue complications, and psychological insulin resistance contribute to delayed insulin initiation, inadequate dose titration, and suboptimal glycemic control worldwide." (PMID 41900895, 2026). "It is well established that excessive body weight and fat distribution impairs insulin secretion and induces insulin resistance." (PMID 41601869, 2026). "Palmitic acid attenuates the insulin signaling pathway through mechanisms that lead to insulin resistance." (PMID 41103188, 2026). "Metabolic health was assessed at baseline (T1) and after six months (T2) using lipid profiles, glucose, insulin, and several indirect indices of insulin resistance and β-cell function, including HOMA-IR, QUICKI, and SPINA indices." (PMID 42124052, 2026). "By reducing the insulin resistance and functional improvement of insulin secretion, physical training has a positive influence on glycemia and the cardiovascular risk is also reduced." (PMID 42162465, 2026). "The insulin-sensitizing potential of each extract was assessed using an in vitro model of palmitic-acid-induced insulin resistance in L6 skeletal muscle cells, followed by Western blot analysis of key insulin-signaling proteins." (PMID 41599356, 2026). "Plasma glucose and insulin levels were measured after 24 hours of salt loading and depletion and insulin resistance was measured by the homeostasis model assessment index (HOMA-IR)." (PMID 41052782, 2026). "Aged β-cell-secreted SASP (e.g. IL-6, TNF-α and CXCL1) can directly inhibit insulin signaling or exacerbate systemic insulin resistance through endocrine pathways." (PMID 41551989, 2026). "Fasting glucose, insulin levels, lipid parameters, and measures of insulin resistance were evaluated." (PMID 41599954, 2026). "The outcome measures included fasting plasma glucose, fasting insulin, homeostatic model assessment of insulin resistance (HOMA-IR), lipid profiles, TG:HDL-C ratio and blood pressure.." (PMID 41761157, 2026). "Firmicutes play a role in insulin signal transduction, glucose metabolism, and improved insulin resistance in T2DM, and the Firmicutes/Bacteroides ratio is considered a marker for diet‐induced gut microbiota dysbiosis." (PMID 41551995, 2026). "Briefly, excess of catecholamines have been shown to disrupt glucose homeostasis through mechanisms such as enhanced glycogenolysis, increased gluconeogenesis, and inhibited insulin secretion, collectively leading to hyperglycemia and insulin resistance." (PMID 40578302, 2026). "The T2DM model, established through a low‐dose STZ injection in conjunction with prolonged HFD exposure, exhibited characteristics of insulin resistance accompanied by comparatively elevated insulin secretion." (PMID 41509193, 2026). "While in vitro studies suggest that IRS-1S307 promotes insulin resistance, knock-in studies in mice suggest that Ser307 positively regulates insulin signaling." (PMID 41535266, 2026).